NEO1 (neogenin 1)
Diseases named in the same sentence as NEO1 in open-access papers (continued):
Sharing a sentence is not in itself a finding about the gene and the disease.
brain tumors (2 papers, 2009 to 2013). "The present study describes the expression of several iron-related genes including hepcidin (HAMP), HFE, neogenin(NEO1), transferrin receptor 1 (TFRC), transferrin receptor 2 (TFR2), and hemojuvelin(HFE2) in normal human brain, brain tumors, and astrocytoma cell lines." (PMID 19386095, 2009). "The hypothesis that hepcidin value changes in brain tumors has emerged in comparison with the corresponding normal tissues, according to variation of other parameters such as, HFE, neogenin (NEO1), receptor 1 for transferrin (TFR) and receptor 2 for transferrin (TFR2)." (PMID 24146699, 2013).
colon carcinoma (2 papers, 2020 to 2023). "Colon cancer patients in NEO1 low expression group were associated with worse T stage (p = 0.013), M stage (p = 0.016) and recurrence (p = 0.003)." (PMID 33088218, 2020). "Firstly, NEO1 expression levels in human colon cancer cell line HCT116, DLD1 and SW480 were examined while human colonic epithelial cell line NCM460 was used as a control." (PMID 33088218, 2020). "Increased expression levels of NTN1 and its receptor NEO1 in the visceral adipose tissue from patients with obesity and colon cancer together with elevated DCC and UNC5B mRNA levels in patients with colon cancer were found." (PMID 36831381, 2023). "To identify the distinct altered biological pathways between NEO1 high expression and low expression group, we performed the GSVA and GSEA by using GSE39582, which contained the most colon cancer samples." (PMID 33088218, 2020).
epilepsy (2 papers, 2023 to 2024). A brain disorder characterized by episodes of abnormally increased neuronal discharge resulting in transient episodes of sensory or motor neurological dysfunction, or psychic dysfunction. "A role of astrocytic NEO1 in protecting against epilepsy has been reported recently." (PMID 36942388, 2023). "Consistently, NEO1 expression was decreased in hippocampal samples of epilepsy patients." (PMID 36942388, 2023).
glioma (2 papers, 2020 to 2023). A benign or malignant brain and spinal cord tumor that arises from glial cells (astrocytes, oligodendrocytes, ependymal cells). "To directly test the putative tumor-suppressive functions of Neogenin, we used a lentiviral vector to stably overexpress human NEO1 in the CRC and Glioma cell lines with low NEO1 expression levels." (PMID 36746934, 2023). "Cells with enhanced NEO1 expression exhibited an impaired ability of migration and invasion in two CRC cell lines (HCT 116, RKO) and two Glioma cell lines (U87MG, U251)." (PMID 36746934, 2023). "NEO1 overexpression attenuated Vimentin in HCT 116 CRC cells and U87MG Glioma cells at the protein level, respectively." (PMID 36746934, 2023). "Furthermore, NEO1-induced pYAP activation was dramatically attenuated by silencing NF2 in both CRC and Glioma cells." (PMID 36746934, 2023). "To experimentally test this hypothesis, we assessed the effects of NEO1 on YAP signaling, and we found that YAP phosphorylation significantly increased after the overexpression of NEO1 in CRC and Glioma cells." (PMID 36746934, 2023). "Furthermore, NEO1 overexpression inhibited the motility of CRC cells (HCT 116) and glioma cells (U251), and this inhibition was partially abolished after silencing NF2." (PMID 36746934, 2023).
hepatoma (2 papers, 2024 to 2026). "In contrast to the observations that Mt2 cleaves Neo1 and markedly reduces Neo1 levels in cultured hepatoma cells, we found that Mt2 stabilizes Neo1 in murine liver." (PMID 41534828, 2026). "We found that Neo1 underwent cleavage of its ectodomain and intracellular domains by α- and γ-secretases, respectively, in hepatoma cells." (PMID 39454953, 2024). "The marked increases of this cell surface fNeo1-TMD/ICD by γ-secretase inhibitors suggest that γ-secretase is the predominant protease to cleave Neo1 intracellular domain in hepatoma cells." (PMID 39454953, 2024). "Based on the molecular weight of shed fNeo1-ECD in the conditioned medium and the localization of the protease domain of α-secretase, α-secretase is predicted to cleave Neo1 extracellularly at a site adjacent to the transmembrane domain in hepatoma cells." (PMID 39454953, 2024). "Both hepatoma cell lines endogenously express low levels of NEO1 and hepcidin." (PMID 39454953, 2024). "We used hepatoma cells and specific inhibitors to determine whether the Hjv-increased Neo1-ECD/TMD in the liver is generated by preventing the proteosome-mediated degradation of cleaved Neo1." (PMID 39454953, 2024). "In hepatoma cells, we found that γ-secretase is the predominant protease to release the Neo1-ICD." (PMID 39454953, 2024). "Our studies in hepatoma cells demonstrated that the generation of Neo1-ECD/TMD is facilitated by the membrane-associated Neo1-binding partner, Alk3, and that the glycosylphosphatidylinositol-anchored Hjv protects Neo1 from netrin-1–mediated degradation of Neo1." (PMID 39454953, 2024). "Since these hepatoma cells do not detectably express most of the genes that are involved in iron homeostasis, these results suggest that in the absence of other iron regulatory proteins, inhibition of γ-secretase proteolysis of Neo1 is insufficient to impact hepcidin expression." (PMID 39454953, 2024).
iron overload (2 papers, 2025 to 2026). "In mice, ablation of Neo1 or Hjv reduces hepcidin and causes iron overload." (PMID 41534828, 2026). "The present study is the first to characterize concurrent dysregulation of TMPRSS6, NEO1, and sHJV in transfusion-driven iron overload among pediatric leukemia patients." (PMID 40805193, 2025). "Our data demonstrate a potential relationship: elevated NEO1 concentrations were observed in individuals with clinically significant iron overload, with apparent correlations to serum ferritin and cumulative PRBC exposure." (PMID 40805193, 2025). "The documented elevation of TMPRSS6 and NEO1 concomitant with reduced sHJV strongly suggests their mechanistic involvement in iron overload, exacerbated by therapeutic and transfusional exposures." (PMID 40805193, 2025).
Obesity (2 papers, 2022 to 2023). Accumulation of substantial excess body fat. "To study the expression patterns of NTN1 and NEO1 in the VAT during obesity, we treated adipocytes and monocytes with different inflammation-associated factors." (PMID 36297056, 2022). "Gene expression levels of NTN1 and NEO1 were upregulated (p < 0.05) in the VAT from patients with obesity with the highest expression in the stromovascular fraction cells compared with mature adipocytes (p < 0.01)." (PMID 36297056, 2022). "We hypothesized that NTN-1 is mainly produced by immune cells constituting the stromal vascular fraction cells (SVFC) from VAT with an essential role in the infiltration of macrophages through its receptor NEO-1 perpetuating the inflammatory state in obesity." (PMID 36297056, 2022). "Therefore, our first objective was to study whether obesity and its associated pathology T2D influence NTN-1 and NEO-1 circulating levels and to analyze the effect of weight loss on their plasma levels." (PMID 36297056, 2022). "Subsequently, we compared the impact of the adipocyte-derived secretome from patients with obesity and NTN-1 on the expression levels of NEO1, DCC, and UNC5B in two human colorectal cell lines, Caco-2 and HT-29." (PMID 36831381, 2023). "To simulate the environment found in the VAT during obesity, we studied the effect of adipocyte-derived factors obtained from patients with OB on NTN1 and NEO1 expression levels in macrophages." (PMID 36297056, 2022).
peritonitis (2 papers, 2012 to 2025). Inflammation of the peritoneum (tissue that lines the abdominal wall and covers most of the organs in the abdomen). "For example, Unc5b is known to be constitutively expressed in monocytes, granulocytes, and lymphocytes, and Neo1 expression has been reported in Ly6Chi inflammatory monocytes in sterile peritonitis models." (PMID 40728980, 2025). "We then proceeded to investigate the functional implications of neogenin during an acute inflammatory response using previously characterized Neo1−/− mice in a model of ZyA induced peritonitis." (PMID 22412855, 2012).
rectal adenocarcinoma (2 papers, 2020 to 2025). "The mutation R1304* of NEO1 occurred in five patients with three cancers (UCEC, rectum adenocarcinoma [READ], and COAD), which were truncated mutations." (PMID 41407823, 2025).
Alzheimer disease (1 paper, 2013). A progressive, neurodegenerative disease characterized by loss of function and death of nerve cells in several areas of the brain leading to loss of cognitive function such as memory and language. "Within the Red module in WM (6c), hub genes included those implicated in other neurological conditions and CNS functioning, including WNK1 (linked to both cardiovascular and Alzheimer’s disease) and NEO1 (involved in nervous system development and apoptosis)." (PMID 23406646, 2013).
anemia (1 paper, 2020). A reduction in the number of red blood cells, the amount of hemoglobin, and/or the volume of packed red blood cells. "This raises the question of whether neuron regeneration or correction of anemia is primarily mediated via the NEO1 or BMP/GDF signaling pathway." (PMID 32576689, 2020).
autism (1 paper, 2021). Persistent deficits in social interaction and communication and interaction as well as a markedly restricted repertoire of activity and interest as well as repetitive patterns of behavior. "Interestingly, we also identified differential mRNA expression of several autism-related genes (Dbh, Aqp4, Neo1, and Dync1h1), which might contribute to alterations in the mice autistic-like phenotypes." (PMID 34645786, 2021).
colorectal adenocarcinoma (1 paper, 2023). The most common type of colorectal carcinoma. "Furthermore, both NTN-1 and ACM were found to increase NEO1 and DCC mRNA levels in two colorectal adenocarcinoma cell lines, together with UNC5B downregulation in HT-29 cells when stimulated with ACM." (PMID 36831381, 2023).
gastric tumors (1 paper, 2014). "Furthermore, analysis of 20 primary human gastric tumors revealed an overall positive correlation between increased active expression of galectin-3 and elevated neogenin-1 expression, except in 6 tissues." (PMID 24930499, 2014).
hemorrhage (1 paper, 2024). Loss of blood from the vascular compartment to the exterior or into nonvascular body space as a result of rupture or severance of the blood vessels. "Modified Rankin Scale (mRS) grades were obtained for these patients six months following hemorrhage, revealing significantly lower NEO1 expression in patients with mRS >2 compared to those with mRS ≤2." (PMID 39107268, 2024).
hyperlipidemia (1 paper, 2022). "Neo-1 inhibition did not significantly alter plasma triglyceride levels or plasma cholesterol levels suggesting that Neo-1 probably does not regulate hyperlipidemia." (PMID 35186922, 2022).
liver cancer (1 paper, 2025). An epithelial or non-epithelial malignant neoplasm that arises from the liver. "We found that NEO1 was positively regulated by HDAC1, 2, and YY1, whereas was negatively regulated by HDAC6 in LIHC, suggesting that NEO1 may play an important role in the proliferation and apoptosis of liver cancer cells." (PMID 41407823, 2025).
liver disease (1 paper, 2022). "According to the recently described potential link between hepatic inflammation and liver disease progression through netrin-1, we found an upregulation of its receptor NEO1 in the liver from patients with T2D." (PMID 36297056, 2022).
melanoma (1 paper, 2023). A malignant, usually aggressive tumor composed of atypical, neoplastic melanocytes. "To explore the role of NEO1 in cancer, we first analyzed the expression of Neogenin in eight tumor models, including tumor colon, glioma, tumor lung, kidney renal clear cell carcinoma, neuroblastoma, liver hepatocellular carcinoma, tumor breast, and melanoma, from TCGA and other public databases." (PMID 36746934, 2023).
monocytic leukemia (1 paper, 2022). "In vitro studies in human visceral adipocytes and human monocytic leukemia cells (THP-1)-derived macrophages were performed to analyze the impact of inflammation-related mediators on the gene expression levels of NTN1 and its receptor NEO1 as well as the effect of NTN-1 on inflammation." (PMID 36297056, 2022).
Moyamoya disease (1 paper, 2023). Moyamoya disease (MMD) is a rare intracranial arteriopathy involving progressive stenosis of the cerebral vasculature located at the base of the brain causing transient ischemic attacks or strokes. "In aggregates, these results suggest a critical role of astrocytic NEO1-loss in the development of a moyamoya disease-like vasculopathy, providing a mouse model for investigating mechanisms of a moyamoya disease-like vasculopathy." (PMID 37273690, 2023).
osteosarcoma (1 paper, 2019). A usually aggressive malignant bone-forming mesenchymal neoplasm, predominantly affecting adolescents and young adults. "The expression levels of BBRN supercomplex (RGMb, BMPR2, and Neo1) in the primary and metastatic osteosarcoma tumors were evaluated by IHC, and the results indicated BBRN supercomplex expression was increased in lung metastases compared with primary osteosarcoma." (PMID 30886151, 2019).
pancreatic ductal adenocarcinoma (1 paper, 2025). An infiltrating adenocarcinoma that arises from the epithelial cells of the pancreas. "In a liver metastasis model of PDAC (pancreatic ductal adenocarcinoma), treatment with a NTN1-neutralizing antibody or tumoral knockdown of Neo1 reduced ZEB1 and SOX9 and decreased tumor progression." (PMID 40777309, 2025).
pancreatic tumor (1 paper, 2025). "Collectively, these data suggest that NTN1 secreted from Kras-mutant pancreatic tumor cells increases the axonogenesis of sympathetic nerves partly through NEO1." (PMID 40777309, 2025). "Treatment of pancreatic tumor organoids with recombinant NTN1 enhanced cell growth, epithelial-mesenchymal transition (EMT), and cancer stemness with the upregulation of ZEB1 and SOX9 through NEO1-mediated activation of focal adhesion kinase (FAK)." (PMID 40777309, 2025).
polyneuropathy (1 paper, 2021). A disease or disorder affecting more than one nerve. "In skin samples of patients with polyneuropathy, NTN1 in proximal and DCC and NEO1 (two attracting receptors) in distal specimens are reduced." (PMID 34576252, 2021).
prostate adenocarcinoma (1 paper, 2025). "NTN1 only predicted the NTN1-RANGAP1 and NEO1 fusion gene in endocrine-associated cancer (OV, BRCA, and prostate adenocarcinoma [PRAD]) in UCEC." (PMID 41407823, 2025).
renal carcinoma (1 paper, 2025). A carcinoma arising from the epithelium of the renal parenchyma or the renal pelvis. "In general, NTN1, NEO1, DSCAM, UNC5C, and UNC5D are all regulated by HDAC members in renal cancer, suggesting that NTN1, NEO1, DSCAM, UNC5C, UNC5D, and especially NEO1 and UNC5C may be essential for the regulation and outcome of renal cancer." (PMID 41407823, 2025).
rotator cuff tear (1 paper, 2025). "In this study, we demonstrate for the first time that netrin-1 and its dependence receptors UNC5B and Neogenin-1 are coordinately upregulated in a rat rotator cuff tear model, with peak expression in the subacute phase of tendon injury." (PMID 40728980, 2025).
signet ring cell carcinoma (1 paper, 2014). A usually aggressive, poorly differentiated invasive adenocarcinoma characterized by the presence of malignant glandular cells in which the nucleus is pressed to one side by the presence of intracytoplasmic mucus. "Interestingly, neogenin-1 was highly detected in signet ring cell carcinoma of diffuse type gastric cancer tissues, which has a metastatic property on the various cancer types." (PMID 24930499, 2014).
thymoma (1 paper, 2025). A neoplasm arising from the epithelial cells of the thymus. "Of these, NEO1 has the strongest correlation (r = − 0.5814), suggesting that EZH2 may alter the expression of NTN1, NEO1, and UNCB-D to promote the occurrence of thymoma." (PMID 41407823, 2025). "Moreover, EZH2 negatively regulates NTN1, NEO1, and UNCB-D in thymoma." (PMID 41407823, 2025).
virus infection (1 paper, 2025). "In summary, we describe the acquisition of the epsin 1 interactome upon virus infection and uncover Neo1 as a novel proviral host factor for IAV." (PMID 40623098, 2025). "While EGFR and Nectin2 were not enriched, Neo1 was enriched 2.78-fold upon virus infection." (PMID 40623098, 2025).